DLK1 (delta like non-canonical Notch ligand 1)
Diseases named in the same sentence as DLK1 in open-access papers (continued):
Sharing a sentence is not in itself a finding about the gene and the disease.
tumor (continued). "Potentially elevated secretion of IL6 and TNF by Snail-expressing cancer cells can therefore not explain the observed Dlk1-Dio3 locus repression in tumor-infiltrating immune cells." (PMID 30190790, 2018). "Bilateralism of the tumours, presence of Reinke crystals and expressions of synaptophysin, Inhibin α, CD56, androgen receptor, DLK1, INSL3, CYP11B1, CYP21A2 and MC2R have all been studied as potential markers, but none of these markers individually can reliably discriminate TARTs from LCTs." (PMID 29038332, 2017). "To evaluate the co-expression of imprinted genes and miRNAs at the 14q32 locus, we analyzed the expression of DLK1-DIO3 cluster genes (DIO3, DLK1, MEG3, and MEG8) and representative 14q32 miRNAs (miR-134, miR-154, and miR-382) in an independent set of 43 osteosarcoma tumor samples." (PMID 26802029, 2016). "Of these, lnc-DLK1-4 (often called MEG3, a well-characterized tumor suppressor) could be annotated to these two gene sets, supporting the utility of this SOM analysis on initial prediction for potential roles of unknown lncRNAs." (PMID 26918340, 2016). "DLK1 is located in the DLK1/MEG3 imprinted locus on human chromosome 14q32.3 and MEG3, coding for a maternally imprinted long noncoding RNA with tumor suppressive function, was also found to be specifically silenced through methylation in NFPAs, but not in other hypophyseal adenoma types." (PMID 23756599, 2013). "Moreover, DLK1 expression is not uniform within tumor tissue, indicating intratumoral heterogeneity." (PMID 39769389, 2024). "In ACC, ADCT-701, a DLK1 targeting antibody-drug conjugate (ADC), shows potent in vitro activity among established cell lines and a new cohort of patient-derived organoids as well as robust in vivo anti-tumor responses in cell line-derived and patient-derived xenografts." (PMID 39416174, 2024). "Furthermore, serum DLK1 correlated with AFP and tumor size in HCC patients." (PMID 35805898, 2022). "An analysis comparing results of the transcriptome profiling of hepatic cell lines and tumor cells in HB and HCC showed significant differences in the level of DLK1 gene expression in HepG2 cells, which may be necessary for driving chemoresistance and potentiating malignancy in cancers." (PMID 34884942, 2021). "It is yet unclear whether or not DLK1 expression is required in tumor cells to be affected by soluble DLK1 secreted into the niche." (PMID 33142235, 2020). "Our experiments indicate that soluble DLK1 affects tumor cell proliferation similarly regardless of whether it was produced by astrocytes or tumor cells." (PMID 33142235, 2020). "Still, we could not ignore the factor that DLK1 staining was detected in 30.5% (107/351) NSCLC tumor cells." (PMID 31661545, 2019). "The frequencies of a single marker expression were 10.4% (DLK1), 6.8% (EpCAM), 4.0% (NCAM), and 2.4% (CK19), indicating that other HPC marker-positive HCCs (approximately 33.7% of the total number of HPC marker-positive tumours) expressed two or more HPC proteins." (PMID 29774107, 2018). "However, the general Dlk1-Dio3 locus upregulation during lung tumorigenesis does not contradict a Snail-mediated locus repression in tumor-infiltrating immune cells, but points towards two possibly independent regulatory mechanisms." (PMID 30190790, 2018). "The role of DLK1 in tumor is not clear, and it acts as either an oncogene or tumor suppressor." (PMID 29348851, 2017). "This suggests that no specific Dlk1 isoform can be attributed to RMS tumor progression." (PMID 23577150, 2013). "Accumulative evidence has demonstrated that increased expression of DLK1 was observed with disease progression and negative prognostic effects in numerous malignancies, and could also recover and promote stemness of tumor cells." (PMID 36671569, 2023). "Interestingly, DLK1 expression itself has been shown to be regulated by hypoxia in other cell systems, suggesting that there may be a DLK1-HIF feedback loop in hypoxic tumor cells." (PMID 33142235, 2020).
tumor (continued). "DLK1 presence did not correlate with other classic prognostic factors such as AFP, tumor node metastasis, or vascular invasion." (PMID 35805898, 2022). "Based on the canonical marker gene expression, 3,085 cells were annotated as tumor cells (GPC3, EPCAM, AFP, ALB, DLK1), while 18,365 cells were designed as non-tumor cells." (PMID 35860547, 2022). "While these two tumor-associated clusters had gene expression profiles similar to that of the DCN-high tumor cell cluster 5, they did not express HB genes including GPC3, DLK1, and DKK1." (PMID 36008377, 2022). "Although some studies suggest the relationship between DLK1 or CK19 and tumour malignant behaviour, they were not confirmed as independent prognostic factors of OS in our study." (PMID 29774107, 2018). "DLK1 is a maternally imprinted, paternally expressed gene coding for the transmembrane protein Delta-like homologue 1 (DLK1), a non-canonical NOTCH ligand with well-described roles during development, and tumor-supportive functions in several aggressive cancer forms." (PMID 34606325, 2022). "Interestingly, when a tumor sample showed a negative or weak staining for AIFM3, it also showed a similar pattern for DLK1 (p < 0.02)." (PMID 33435319, 2021).
cancer (67 papers, 2005 to 2026). A tumor composed of atypical neoplastic, often pleomorphic cells that invade other tissues. "The broad role of DLK1 in development and disease, coupled with its restricted expression profile in adults, have implicated DLK1 as a potential therapeutic target in both cancer and muscle wasting diseases." (PMID 40593645, 2025). "In 3T3-L1 preadipocytes, miR-15a fine-tunes the level of DLK1; this gene is implicated in cellular growth and plays multiple roles in development, tissue regeneration, and cancer." (PMID 31434294, 2019). "DLK1-Dio3 miRNA are differentially expressed in various human pathological conditions and have been implicated in the pathogenesis of various human diseases, especially cancers." (PMID 27070142, 2016). "We highlight key novel mechanistic insights, translational challenges, and future opportunities to exploit DLK1 as a precision therapeutic target in these high-need cancer subtypes." (PMID 42023826, 2026). "Elevated DLK1 expression has been documented across a spectrum of cancers affecting various organ systems, including the endocrine system, gastrointestinal tract, lungs, liver, kidneys, brain, breast, sarcomas, and both pediatric and adult blood cancers." (PMID 39595993, 2024). "In various other cancers, DIO3 has been implicated through its association with the imprinted delta-like non-canonical Notch ligand 1 (DLK1)-DIO3 locus." (PMID 39170648, 2024). "In a two-step hepatic carcinogenesis mouse model, the expression of DLK1 and cancer stem cell markers was found to be upregulated in liver tumors, and knockdown of DLK1 inhibited liver tumor growth." (PMID 39769389, 2024). "DLK1 expression characterizes drug-resistant tumors, since this gene allows cancer cells to maintain a stem-like phenotype." (PMID 36673024, 2023). "These authors assessed the expression of DLK1 positive cells in some of the human cancer-derived cell lines most commonly used in laboratories." (PMID 35805898, 2022). "In particular, the role of DLK1 in cancer stem cell niches has been recently well characterized in brain cancer." (PMID 34606325, 2022). "To exemplify how these lincRNA genomic clusters provided insight into the pathogenesis of cancer, we examined a lincRNA genomic cluster mapping to Dlk1-Dio3 imprinted locus." (PMID 34906173, 2021). "The epigenetic dysregulation of the Dlk1-Dio3 miRNA cluster has been documented in various cancer types, such as melanoma, leukemia, ovarian cancer, breast cancer, bladder cancer, metastatic hepatoblastoma, and implicated in tumorigenesis." (PMID 34062726, 2021). "Yet, the vast majority of studies other than cancer fields, however, reported DLK1 to inhibit cell proliferation." (PMID 31661545, 2019). "How the Snail-mediated downregulation of the Dlk1-Dio3 locus affects the activity of lymphocytes and other immune populations in a cancer context needs to be evaluated in functional studies." (PMID 30190790, 2018). "We show herein that Snail-expressing cancer cells can repress the Dlk1-Dio3 locus activity across several immune populations." (PMID 30190790, 2018). "In conclusion, the data presented in this study proved the role of DLK1 in cancer invasion and explored the molecular mechanism behind this function, making DLK1 a new candidate gene in cancer metastasis studies." (PMID 24621612, 2014). "dlk1 aberrantly expressed in 36.7% (11/30) of the tumor tissues of NSCLC compared with their adjacent cancer lung tissues." (PMID 20959062, 2010). "Additionally, C2cd4b, a marker of acute inflammation, and Dlk1, a driver of Wnt signaling, lung repair and stemness, and cancer stemness, were downregulated." (PMID 40356899, 2025).
cancer (continued). "DLK1 is expressed in cancer stem cells, and its expression is regulated by Wnt/β-catenin signaling." (PMID 39769389, 2024). "Therefore, CBA-1205 has potential as a treatment option for cancers in addition to HCC that express DLK1." (PMID 39769389, 2024). "Using scRNA-seq data, we investigated the expression of genes involved in stromal-like signature (FAP, VIM, and ITGB1); cancer-associated fibroblasts (CAFs; POSTN and ACTA2); as well as COL1A1, SULF1, TCF21, and DLK1, which were previously associated with FAP-high or FAP-low CAF phenotypes in OC." (PMID 39634630, 2024). "Recent studies suggest that drug resistance in cancers may stem from the survival of cancer cells exhibiting a stem cell phenotype, and DLK1 may play a crucial role in regulating and maintaining this phenotype." (PMID 39595993, 2024). "Indeed, DLK1’s elevated expression has been identified in pediatric cancers as well as aggressive and therapy-resistant adult cancers." (PMID 39595993, 2024). "DLK1, a transmembrane protein belonging to the Notch ligand family, plays an important role in stem cell regulation, cancer differentiation, tissue differentiation during development and the maintenance of cancer stem cell‐like cells." (PMID 36977657, 2023). "Together with Afp and Igf2, the expression of stem cell markers Dlk1, Gpc3 and Epcam appeared to be higher in clusters 7 and 16, which may represent the bona fide cancer cells." (PMID 37414763, 2023). "In a similar manner, DLK1 also plays a fundamental role in regulating cancer cell plasticity toward a less differentiated, more stem-like phenotype that may confer increased aggressiveness and therapeutic resistance." (PMID 34606325, 2022). "A similar role for DLK1 as a stem cell niche factor was also described in another type of cancer." (PMID 34606325, 2022). "A better understanding of DLK1 regulation and signaling may enable therapeutic targeting of cancer stemness by interfering with DLK1 release and/or intracellular signaling." (PMID 34606325, 2022). "In cancer, DLK1 acts as an oncogene, and elevated expression has been reported in endocrine and non-endocrine malignancies including prostate and ovarian cancers, neuroblastoma, pancreas and colon adenocarcinomas, non-small and small cell lung cancer, HCC, and Wilm’s tumor." (PMID 35805898, 2022). "A better understanding of these differences and of DLK1 role in cancer stemness may open the door for therapeutic targeting approaches, thus providing an alternative tool for fighting highly lethal cancer types." (PMID 34606325, 2022). "DLK1 is overexpressed in several cancers and is related to bad prognoses." (PMID 35805898, 2022). "The dysregulation of Dlk1-Dio3 miRNAs has been identified in various types of cancers." (PMID 34062726, 2021). "Deregulations of Dlk1-Dio3 imprinted domain were involved in various diseases especially cancers." (PMID 34906173, 2021). "Since ACM contains many other different factors that may influence cancer cell growth, we then directly investigated the effects of soluble DLK1 with 2 different approaches." (PMID 33142235, 2020). "Because Dlk1 expression is detected in proliferative hepatoblasts from the fetal liver and in cancer cells, Dlk1 expression may also reflect the proliferative ability of mesenchymal progenitors." (PMID 31277245, 2019). "We proposed that the targeting endogenous DLK1 could suppress the malignant behaviors of HCC cells possibly through interfering cancer stem/progenitor cells." (PMID 27683116, 2016). "Up-regulated expression of DLK1/Notch1 has been detected in various human cancers." (PMID 27455311, 2016). "Furthermore, our data demonstrated that DLK1 promoted cancer cell invasion through upregulation of MMP9 expression and enhancement of its extracellular activity, which are dependent on the Notch signaling pathway." (PMID 24621612, 2014).
cancer (continued). "Based on the hypothesis that DLK1-induced cancer cell invasion was mediated by upregulation of MMP9, the expression of MMP9 upon DLK1 stimulation was analyzed by both real-time PCR and Western blotting." (PMID 24621612, 2014). "Taking these findings together, we hypothesize that Notch signaling might be involved in DLK1-induced cancer cell invasion." (PMID 24621612, 2014). "Among those genes, DLK1 showed more than two-fold higher expression in primary tumors with lymph node metastasis, suggesting that DLK1 may play roles in cancer metastasis." (PMID 24621612, 2014). "A transwell assay showed that DLK1 overexpression significantly promoted cancer cell invasion." (PMID 24621612, 2014). "Because our study suggests a regulatory relationship between DLK1 and NOTCH1, it is natural to hypothesize that the abnormal expression of NOTCH1 in cancers is partially the consequence of aberrant expression of DLK1." (PMID 24621612, 2014). "The overexpression of DLK1 has been observed in numerous types of cancer, including MDS and AML." (PMID 23946804, 2013). "As described for IGF2/H19, epigenetic changes at DLK1/GTL2 occur in human cancers." (PMID 15798773, 2005). "Therefore, depletion of DLK1-expressing cancer cells by CBA-1205 may be a useful HCC treatment strategy." (PMID 39769389, 2024). "CBA-1205 may be a potential therapeutic agent targeting DLK1 in immuno-excluded cancers." (PMID 39769389, 2024). "Therefore, DLK1 may be a candidate cancer stem cell marker in HCC in addition to its function as a HPC marker." (PMID 39769389, 2024). "MiR-127 gene is located in the imprinted region Dlk1/Gtl2 and transcribed in an antisense orientation to a retrotransposon-like gene (Rtl1), and the expression of miR-127 has been shown to undergo DNA methylation regulation in mouse embryos and human cancer cells." (PMID 22720056, 2012). "DLK1-positive sub-populations have also been reported to express stem cell and progenitor cell markers (Nanog, Oct3/4, SOX2) and exhibit cancer stem cell–like characteristics, including resistance to chemotherapeutic agents." (PMID 39769389, 2024). "Moreover, in recent years it has been suggested that DLK1 plays a fundamental role in regulating cancer cell plasticity toward a less differentiated, more stem-like phenotype that may confer increased aggressiveness and therapeutic resistance and disease relapse across diverse malignancies." (PMID 39595993, 2024). "Specifically, increased expression of GPC3, DLK1, and HMGA2 are genes that define the driving pathways of HB, and these genes have also been previously reported as cancer stem cell markers in HB7,38." (PMID 34497364, 2021). "In the comprehensive prognostic signature, genes such as NFKB2, DLK1, KANK1, play important roles in cancer biology." (PMID 33193606, 2020). "First, we targeted the following loci given the initial observation from TCGA: five imprinted domains (PEG3, H19/IGF2, DLK1/GTL2, MEST, GNAS) and four cancer genes (APC, MLL3, MGMT, ELF3)." (PMID 26338779, 2015). "This study has the potential to shed light on the role of DLK1 in CD34+CD38− cells with regard to the regulation of the cell cycle and apoptosis, and to provide mechanistic insights into the progression of malignant tumors." (PMID 23946804, 2013). "This reduction correlated with increased expression of stem cell markers, such as PROM1, CK19, DLK1, SALL4, and EPCAM, suggesting that low SLC2A2 levels may promote cancer stem cell traits, malignancy, and therapeutic resistance." (PMID 40279337, 2025). "DLK1, a surface protein belonging to the NOTCH noncanonical ligand family, is co-expressed with stem cell markers in various human cancers and is therefore implicated in regulating stem cell properties." (PMID 39595993, 2024). "DLK1 expression has been reported in various cancers in addition to HCC, and thus CBA-1205 may also be a therapeutic option for patients with other cancers." (PMID 39769389, 2024).